CD4 (CD4 molecule)
Diseases named in the same sentence as CD4 in open-access papers (continued):
Sharing a sentence is not in itself a finding about the gene and the disease.
pancreatic cancer (249 papers, 2000 to 2026). "Gene ontology analysis confirmed that the differentially enriched regions from both pancreatic cancer-specific and CD4+ T cell open chromatin were significantly associated with pancreatic cancer related pathways." (PMID 41225146, 2025). "Previous studies have demonstrated that a more favorable survival in pancreatic cancer is strongly associated with a high infiltration of CD4+ effector and cytotoxic T cells, along with a low level of Tregs, rather than a high total T-cell population." (PMID 38988711, 2024). "In our investigation, we found that higher levels of HLA-DR+ CD4+ T lymphocytes were associated with a decreased risk of pancreatic cancer." (PMID 38933268, 2024). "Among these, 16 immune cell phenotypes, including CD11c+ monocyte % monocyte, are regarded as risk factors for pancreatic cancer, while 11 immune cell phenotypes, such as CD4 Treg AC are regarded as protective factors for pancreatic cancer." (PMID 38933268, 2024). "High infiltration of CD4+ T cell was associated with improved survival in pancreatic cancer patients while CD8+ T cell infiltration didn’t have an impact on overall survival." (PMID 37287989, 2023). "Post treatment VAS and change of peripheral CD4+ T cells are independent risk factors affecting the prognosis in patients with unresectable pancreatic cancer after HIFU treatment." (PMID 37792639, 2023). "Through single-cell RNA sequencing of human pancreatic cancer, we discovered that tumor-infiltrating CD4+ T cells express TCF7, encoding for the transcription factor TCF1." (PMID 36239683, 2023). "There is a widespread belief that CD4+ T cells compromise the majority of T cells in pancreatic cancer and are positively associated with tumor metastasis and negatively associated with OS." (PMID 33224872, 2020). "In pancreatic cancer, the ratio of Tregs to CD4+ T (%Treg) has demonstrated a significant association with shorter survival, while tumor-infiltrating CD4+ Thigh/CD8+ Thigh/%Treglow independently predicted longer overall survival." (PMID 33080912, 2020). "This group was enriched with pancreatic cancer-related oncogenic pathways and mutations and was associated with invasion, metastasis, poor survival, and significantly lower levels of CD4+ T cell infiltration." (PMID 31612115, 2019). "It is generally considered that CD4+ T cells compromise the majority of T cells in pancreatic cancer and are positively associated with metastasis and negatively associated with survival." (PMID 31612115, 2019). "In one murine study, the presence of TNFα and IL-17-producing CD4+ T cells in pancreatic cancer was associated with relatively aggressive disease." (PMID 27777771, 2016). "Again, we didn’t observe any association between circulating plasma MSLN levels and CD4+ T cell responses in pancreatic cancer subjects at the time point analysis." (PMID 24520352, 2014). "We first evaluated the influence of IL-12 and IL-27, as single agents and in association, on the polarization of CEA-specific Th2 CD4+ T cell clones from a pancreatic cancer patient." (PMID 19798410, 2009). "Notably, differential enrichment between healthy donors and cancer patients was observed at open chromatin regions often associated with breast or pancreatic cancer, as well as CD4+ T cells." (PMID 41225146, 2025). "The inverse relationship between certain immune cell types, such as CD4+ CD8dim leukocytes, and pancreatic cancer risk suggests a protective immune response that may be compromised during cancer development." (PMID 39906083, 2025). "Moreover, GSDMD activation and function were conserved in human CD4+ T cells and associated with favorable prognosis and improved response to anti–PD-1 immunotherapy in colonic and pancreatic cancer." (PMID 40759573, 2025). "Furthermore, the Th2: Th1 ratio in pancreatic tumours has been linked to patient prognosis, and multiple lines of evidence support a role for CD4+ T-cells in promoting pancreatic tumorigenesis." (PMID 36138073, 2022).
pancreatic cancer (continued). "The resistance of pancreatic cancer cells is also associated with changes in CD4+ memory T cells." (PMID 34671397, 2021). "Neutrophil and CD4+ cells, as the major inflammatory cells, might increase the risk of carcinogenesis and tumor progression of pancreatic cancer." (PMID 33102222, 2020). "Notably, in pancreatic cancer patients, an increased level of tumor-infiltrating CD4+ T cells is associated with improved survival." (PMID 29670543, 2018). "In addition, our analysis indicates that adrenate (-8.39%, 95% CI: -18.3%, 1.54%) plays a partial mediating role in the association between CD11c+ monocyte and pancreatic cancer, while cortisone (-26.6%, 95% CI: 138%, -84.8%) acts as a partial mediator between HLA DR+ CD4+ AC and pancreatic cancer." (PMID 38933268, 2024). "Higher VAS score and decreased CD4+ T cell ratio after HIFU treatment may be potential survival risk factors for patients with unresectable pancreatic cancer, which can be easily obtained in clinical work and help to evaluate patients' feedback on HIFU therapy early." (PMID 37792639, 2023). "Univariate cox regression analyses identified that activated CD4 T cell, activated dendritic cell, CD56bright natural killer cell, central memory CD4 T cell, gamma delta T cell and type 2 T helper cell were risk factors of pancreatic cancer prognoses in m6A cluster A." (PMID 34603372, 2021). "In the case of pancreatic cancer, individuals with long-term survival demonstrate greater diversity and abundance of their intratumoral microbiomes, along with higher frequencies of CD4+ and CD8+ T cells, than short-term survivors." (PMID 39966840, 2025). "Utilizing XGBoost and RF, we pinpointed 10 genes closely related to pancreatic cancer, culminating in the identification of RAP1GDS1, TOP2A, ADK, POLL, CD44, and CD4 as pivotal genes linked to hypoxia in pancreatitis." (PMID 40787634, 2025). "Using confocal microscopy to interrogate tumor tissues, GSDMD activation in CD4+ T cells within both human colonic and pancreatic tumor tissues was further confirmed by anti–GSDMD-N staining." (PMID 40759573, 2025). "In this study, we also found that apCAFs were negatively correlated with cytotoxic T cells and IFN‐γ+CD4+ T cells in pancreatic cancer tissues." (PMID 39887656, 2025). "In contrast, pancreatic cancer long-term survivors exhibit a more diverse and abundant intratumoral microbiome, along with higher frequencies of CD4+ and CD8+ T cells, compared to short-term survivors." (PMID 39966840, 2025). "To understand the mechanism behind pancreatic tumor regression upon treatment with engineered DCs, we employed immunohistochemistry (IHC) analysis to assess the tumor infiltration of CD4+ and CD8+ T cells." (PMID 40733726, 2025). "Immunofluorescence staining revealed that CD4 FOXP3 cell numbers in PT tissues from patients with late-stage pancreatic cancer were significantly higher than those in patients with early-stage pancreatic cancer." (PMID 40303346, 2025). "In this study, multi-colour fluorescent staining revealed a notable increase in CD4 T cells exhibiting exhaustion characteristics surrounding tumor cells in patients with advanced pancreatic cancer." (PMID 40303346, 2025). "aCD40 treatment significantly increased tumoral expression of CCL5, potentially contributing to the recruitment of Granzyme B + CD4 + T cells from TDLNs to the tumor bed, as previously reported in pancreatic cancer models." (PMID 40585246, 2025). "Multifluorescent staining of pancreatic cancer tissues was conducted using antibodies against CD4 (white), CD8 (light blue), CD20 (pink), FOXP3 (red), VIM (green), and panCK (yellow), along with 4',6-diamidino-2-phenylindole, dihydrochloride (DAPI)." (PMID 40303346, 2025). "Immune cell infiltration, including CD4+ T cells, is rarely observed in cold tumors due to the immunosuppressive environment of pancreatic cancer." (PMID 39409930, 2024).
pancreatic cancer (continued). "Mediation analysis revealed that Interleukin-6 (IL-6), “CD4 on naive CD4+ T cell” and “SSC-A on HLA DR+ Natural Killer” mediated the causal effects of gut microbiota on pancreatic cancer." (PMID 39119339, 2024). "Elena discovered that CD4+T cells in the serum of pancreatic cancer patients exhibited increased production of the Th2 cytokine IL-5, resulting in a phenotype of tumor-infiltrating lymphocytes that favored Th2 cells." (PMID 38828409, 2024). "A study from early 2014 utilized transgenic mice to delete α-SMA+ myofibroblasts in pancreatic cancer, resulting in diminished animal survival correlated with increased CD4+Foxp3+ Tregs." (PMID 38672552, 2024). "Our study supports this viewpoint, suggesting an inverse correlation between HLA-DR+ CD4+ antigen-presenting cells and pancreatic cancer (ORIVW=0.920, 95%CI=0.873–0.968)." (PMID 38933268, 2024). "In a mouse model of pancreatic cancer, the injection of recombinant IL-6 not only elevated corticosterone levels but also led to the depletion of immune cells such as CD4+T cells, CD8+T cells, and NK cells." (PMID 38828409, 2024). "The results reported in the previous study are consistent with our own findings (ORIVW=1.458, 95%CI=1.138–1.868), indicating that cortisone acts as a mediator, attenuating the impact of HLA DR+ CD4+ T lymphocytes on pancreatic cancer." (PMID 38933268, 2024). "Cortisone levels negatively regulated pancreatic cancer in conjunction with HLA DR+ CD4+ AC (ME=-0.0223; MP=-26.6%)." (PMID 38933268, 2024). "Our data so far shows that, in addition to the previously known tumor-supportive role of WNT signaling in epithelial cells, its function in CD4+ T cells contributes to pancreatic cancer growth, at least in part through promoting immune suppression." (PMID 36239683, 2023). "We conditionally inactivated Tcf7 in CD4 expressing T cells in a mouse model of pancreatic cancer and observed changes in the tumor immune microenvironment, including more CD8+ T cells and fewer regulatory T cells, but also compensatory upregulation of PD-L1." (PMID 36239683, 2023). "In patients with pancreatic cancer, Treg cells are an important component involved in the inhibition of tumor immune response by disordering the functions of CD4+ T and CD8+ T cells, macrophages, NK cells and DC cells." (PMID 37064113, 2023). "To functionally dissect the role of T cell Tcf7 in pancreatic cancer, we generated Cd4-CreERT2;Tcf7fl/fl mice, where Tcf7 can be conditionally inactivated in CD4-expressing T cells." (PMID 36239683, 2023). "Further CD4/FOXP3 immunofluorescence co-staining confirmed the higher levels of infiltration of Treg cells in pancreatic cancer tissue." (PMID 37753069, 2023). "We inactivated Tcf7 in CD4+ T cells and implanted pancreatic cancer cells from the well-characterized KPC mouse model into the pancreata of syngeneic C57BL/6J mice." (PMID 36239683, 2023). "Treg cells infiltrating the pancreatic cancer microenvironment exhibited low expression of CD4 molecules and displayed a mature differentiation state, primarily derived from CD4+ T cells." (PMID 37753069, 2023). "Further, in this work, we focused on the role of TCF1 in CD4+ T cells, as they are the main suppressive lymphocyte populations in pancreatic cancer, based on past work by several groups including ours." (PMID 36239683, 2023). "The results showed that IDO1 expression levels in pancreatic cancers were related to CD4+ memory T cells (r, 0.61), M1-like macrophages (r, 0.46), and CD8+ T cells (r, 0.19) but not other immunosuppressive cells, consistent with our immunostaining results." (PMID 36517670, 2023). "Here we confirm the capability of this combination therapy to dramatically, and durably, control pancreatic cancer growth in an orthotopic model and that the immune memory to this cancer is primarily a function of CD4+ T cells." (PMID 37123403, 2023).
pancreatic cancer (continued). "It was recently shown that the CCL17-eluting scaffold prevents tumor progress in pancreatic cancer by attracting CCR4+CD4+ T cells." (PMID 37371612, 2023). "In line with this, murine pancreatic cancer cells reportedly converted naïve T cells to CD4+FOXP3+ Treg cells by releasing TGFβ." (PMID 38038865, 2023). "The anti-CD134 agonist antibodies increased CD4+ T cells in pancreatic cancer mouse models and have a synergistic effect with anti-PD-1 inhibitor to eradicating tumor." (PMID 36960067, 2023). "We showed that VISTA significantly reduces the TNFα and IFNγ expression of CD4+ or CD8+ T cells cocultured with pancreatic tumor cells." (PMID 37190254, 2023). "In the context of the immune landscape, data from pancreatic cancer suggests that high tumor infiltration of CD4+ and CD8+ T cells, low Tregs, and a high M1/M2 macrophage ratio are all associated with improved survival in pancreatic cancer." (PMID 36368129, 2023). "Whereas infiltration of cytotoxic CD8+ T cells was unaffected by neoadjuvant chemotherapy, the frequency of conventional CD4+ T cells was increased, and the proportion of Tregs was reduced in the pancreatic tumor microenvironment after neoadjuvant treatment." (PMID 36509285, 2022). "Intriguingly, subsequent analysis indicated that FBW7 expression was positively correlated with CD8 and CD4 T cell infiltration in renal cancer, liver cancer and pancreatic cancer." (PMID 35081978, 2022). "An increase in CD4 cytotoxic T cells was found in a mouse pancreatic cancer model after the administration of an antigen-specific dendritic cell (DC)-targeted vaccine, and this effect was enhanced when combined with anti-CTLA4 therapy." (PMID 35572552, 2022). "In pancreatic cancer immune microenvironment, anti-tumor immune cells such as CD4+/CD8+ T cells, NK cells and DCs are less, while immune-suppressive cells such as Tregs, MDSCs and TAMs are abundant." (PMID 36405738, 2022). "IL6 overexpression has also been reported to promote Th17 differentiation of CD4+ T-cells with anti-tumour activity in a transplantable murine model of pancreatic cancer." (PMID 36138073, 2022). "Animal experiments have also confirmed that Th17 cells promote the upregulation of CD4+ T lymphocytes in the tumor microenvironment, thus inhibiting tumor growth and prolonging survival in a mouse model of pancreatic carcinoma." (PMID 35368661, 2022). "More recently, an hTERT (human telomerase reverse transcriptase) specific TCR was isolated from a CD4 T cell clone from a vaccinated pancreatic cancer patient and expressed in primary CD4 and CD8 T cells." (PMID 34064410, 2021). "Depletion of CD4+ T cells from MD4 mice resulted in significantly increased pancreatic tumor growth compared to control MD4 tumors, whereas depletion of CD8+ T cells showed a non-significant trend towards increase in tumor growth compared to isotype controls." (PMID 35046933, 2021). "As a result of the moderate host modulation by our 2 Gy TBI, we found increased numbers of highly active, effector memory Tag-Th1 cells and endogenous CD4+ T cells in the pancreatic tumor tissue, enabling a highly effective therapeutic response." (PMID 34335959, 2021). "In this study, immunohistochemical analysis showed that the tumor cells of patients with early postoperative liver metastasis of pancreatic cancer had higher proliferative activity and less CD4+ T cells infiltration." (PMID 34485300, 2021). "On the other hand, the expression of PTPRO indicated a weak correlation with CD4+ T cells (r = 0.031, P = 6.84e-01) and B cells (r = 0.025, P = 7.45e-01) in pancreatic cancers." (PMID 35003364, 2021). "A recent study found that high CD4+/CD3+ ratio together with a low α-SMA/vimentin ratio on CAFs was correlated with shorter overall survival in pancreatic cancer of the body and tail." (PMID 34203869, 2021). "Orthotopic pancreatic tumours had fewer CD4+ and CD8+ T cell infiltrates than subcutaneous tumours and a larger fraction of SiglecF+ granulocytes." (PMID 34784792, 2021).
pancreatic cancer (continued). "Collectively these data suggest that BCR activation promotes pancreatic cancer growth largely through suppression of CD4+ T cell responses in vivo." (PMID 35046933, 2021). "In the presence of pancreatic cancer microorganisms, immunosuppressive CD206+ M2-like tumor-associated macrophages (TAMs) increased, M1-like TAMs decreased, CD4+ T cell differentiation to Th1 cells decreased and cytotoxic CD8+ T cells decreased." (PMID 33897888, 2021). "In RIP1-Tag2, we found increased numbers of effector memory-like Tag-Th1 and endogenous CD4+ T cells in the pancreatic tumor tissue after TBI, accompanied by a tumor-specific Th1-driven immune response." (PMID 34335959, 2021). "Immunohistochemical analysis showed that the pancreatic cancer cells of patients with early postoperative liver metastasis had higher proliferative activity, while the infiltration of CD4+ T cells in tumor specimens was less." (PMID 34485300, 2021). "More detailed studies are necessary to illustrate the specific role of each CD4+ T lymphocyte subset in pancreatic cancer." (PMID 33224872, 2020). "The authors demonstrated the presence of basophils in TDLNs in this model of pancreatic cancer and provided evidence that cancer-associated fibroblasts (CAFs) released TSLP which activated DCs to produce IL-3 from CD4+ T cells." (PMID 33013885, 2020). "On the other hand, the gut microbiome from a short-term survivor of pancreatic cancer promoted pancreatic tumor growth in a mouse model via increasing the infiltration of CD4+FOXP3+ and myeloid-derived suppressor cells." (PMID 32962112, 2020). "Remarkably, in vivo depletion of Gr-1+ cells in tumor-bearing mice led to a significant reduction in Treg cells (CD4+Foxp3+) in the pancreatic tumors." (PMID 32038621, 2019). "In a murine model of pancreatic cancer, the conversion of CD4+CD25− naïve T cells into Foxp3+ Tregs was shown to be mediated by TGF-β." (PMID 30987642, 2019). "A significant delay in pancreatic intraepithelial neoplasia (PanIN) was reported in spontaneous pancreatic tumor model KC mice that received weekly CD4-depleting antibodies." (PMID 30959852, 2019). "γδ T cells infiltrated in pancreatic cancer tissues can restrain CD4+ T cell and CD8+ T cell activation by expressing high levels of the immune check point proteins PD-L1 and Galectin-9, thereby negating adaptive anti-tumor immunity." (PMID 31064389, 2019). "In conclusion, we found that CD4+ naïve/memory ratio can be a novel prognostic biomarker for advanced pancreatic cancer." (PMID 30767430, 2019). "In particular, the KRASG12D mutation and MEK/ERK pathway activation was shown to up-regulate production of IL-10 and TGF-β, thus promoting CD4 T cells conversion in Tregs in pancreatic cancer." (PMID 31665076, 2019). "While the response of type 2 T helper cells (Th2) is critical for imparting tolerance to tumors, the immune response of CD4+ T-cell-mediated type 1 T helper (Th1) is known to promote the death of pancreatic cancer cells." (PMID 29670543, 2018). "We have now investigated the potential of PD1-CD28 fusion protein-transduced CD4+ T cells alone or in combination with CD8+ T cells for immunotherapy of pancreatic cancer and non-Hodgkin lymphoma." (PMID 30214445, 2018). "In summary, our results indicate that PD1-CD28 fusion protein transduced CD4+ T cells have the potential to overcome the PD-1-PD-L1 immunosuppressive axis in pancreatic cancer and non-Hodgkin-lymphoma." (PMID 30214445, 2018). "In gastric and pancreatic cancer, increased intratumoral IL-22 producing CD4+ T cells correlated with disease's progression and predicted poor patient survival." (PMID 27489357, 2016).